LINC02273 (long independently transcribed non-coding RNA 2273)
Gene: Long non-coding RNA gene on chromosome 4 (152,090,459 to 152,110,159, forward strand). Ensembl gene ENSG00000245954.
Diseases named in the same sentence as LINC02273 in open-access papers:
LINC02273 is named in the same sentence as 2 diseases in open-access papers, as found by Europe PMC text mining. Sharing a sentence is not in itself a finding about the gene and the disease. The quoted sentences say what the papers report.
cancer (1 paper, 2019). A tumor composed of atypical neoplastic, often pleomorphic cells that invade other tissues. "Gene ontology analysis showed that these genes were significantly associated with cancer development and metastasis, such as PI3K-Akt signaling pathway, MAPK signaling pathway, and focal adhesion, supporting the role of LINC02273 in cell proliferation and metastasis processes." (PMID 31856843, 2019).
LINC02273 also shares sentences with these, for which no sentence is quoted: breast carcinoma (1 paper).